COL10A1 (collagen type X alpha 1 chain)
Diseases named in the same sentence as COL10A1 in open-access papers (continued):
Sharing a sentence is not in itself a finding about the gene and the disease.
tumor (continued). "Thus, we strongly suspect that SYNPO2L regulates tumor-associated fibroblast infiltration by controlling COL10A1, thereby playing its role." (PMID 39247832, 2024). "Furthermore, our subsequent experiments also found that tumors secrete COL10A1, which, in conjunction with tumor-associated fibroblasts, guides epithelial tumor cells towards mesenchymal tumor cells, thus mediating tumor cell metastasis." (PMID 39247832, 2024). "Besides, COL10A1 expression is related to tumor mutational genes and filtration levels of various immune cells in tumor microenvironments." (PMID 37006317, 2023). "Immune assays revealed that COL10A1 expression was associated with tumor-filtrating immune cells, like CD8 T cells, cytotoxic cells, DC, eosinophils, iDC, macrophages, mast cells, NK CD56dim cells, NK cells, pDC, T helper cells, Tem, Th1 cells, Th17 cells, and Treg." (PMID 36276283, 2022). "In addition, we found that COL10A1 was significantly associated with CD11c + DC, which is a key target of Treg cells and is involved in immunosuppression in the tumor microenvironment." (PMID 36105715, 2022). "The ectopic expression of COL10A1 is considered to be tightly associated with tumor metastasis." (PMID 33324550, 2020). "Altered expression of COL11A1/COL10A1 is associated with tumor development/progression." (PMID 27857161, 2016). "Moreover, in another study, we showed that high plasma levels of COL10A1 are associated with advanced tumor stage in GC patients, and the elevated expression occurs from the beginning of carcinogenesis, in the early stages, and its increased level remains elevated during cancer progression." (PMID 41303526, 2025). "Elevated COL10A1 expression levels have consistently been observed across various malignant tumour types (including colon, lung, oesophageal, gastric, breast and bladder cancer) and are strongly linked to tumour progression, invasion, metastasis and angiogenesis." (PMID 39656597, 2024). "Collectively, this study establishes a bidirectional signaling loop between CAFs, tumor cells, and immune cells, positioning COL10A1+Fib as a potential pivotal cell type in metastasis-related immune suppression—providing new insight into CAF heterogeneity." (PMID 40826474, 2025). "Thus, COL10A1 is associated with common matrisome features that drive cancer progression, suggesting that ColX-associated genes may broadly play important roles in the development, maintenance, and pro-metastatic function of the tumor microenvironment." (PMID 39939916, 2025). "Data available from the literature indicate that COL10A1 overexpression can affect the balance between tumor cell proliferation and apoptosis, thus sustaining the carcinogenesis process in different types of cancer." (PMID 41303526, 2025). "COL10A1+Fib were significantly enriched in tumor tissues and their proportion increased progressively with TNM stage." (PMID 40826474, 2025). "There are compelling reasons to extrapolate from the roles that COL10A1 plays in OA to putative functions within the tumor microenvironment." (PMID 39939916, 2025). "For example, in HNSCC, human bone marrow-derived MSCs (hBM-MSCs) transfected with miR-101-3p mimics produced EVs enriched with miR-101-3p, which effectively suppressed tumor progression by downregulating Collagen Type X Alpha 1(COL10A1)." (PMID 41254732, 2025). "Multiplex immunofluorescence revealed CD18 localization predominantly in CD163+ or CD206+ macrophages (Primary Tumor: n = 35), with strong positive correlation between COL10A1 and CD18 expression (R > 0.5, P < 0.001)." (PMID 40826474, 2025). "Bulk transcriptomic data from TCGA + GTEx and GSE44076 confirmed that COL10A1 expression was significantly upregulated in tumor tissues, with higher expression in CAFs compared to normal fibroblasts." (PMID 40826474, 2025). "To evaluate the effect of COL10A1 overexpression on tumor processes, we first analyzed COL10A1 expression in GC cell lines Hs746T, AGS, and NCI-N87." (PMID 41303526, 2025).
tumor (continued). "COL10A1 has also been identified as a potential biomarker for early diagnosis of GC, as its increased expression occurs in early tumor stages and remains elevated during cancer progression." (PMID 41303526, 2025). "Together, these results highlight COL10A1 as a key element of the tumor microenvironment that contributes to aggressive GC phenotypes through remodeling of cellular signaling and EMT regulation." (PMID 41303526, 2025). "This framework explains the particularly aggressive clinical behaviour and immune-checkpoint-blockade resistance of CMS4 tumours, and highlights COL10A1+Fib as a tractable stromal target for overcoming the immune-refractory nature of this subtype." (PMID 40826474, 2025). "We demonstrate that COL10A1+Fib promotes epithelial-to-mesenchymal transition (EMT) in tumor epithelial cells via COL10A1 collagen secretion, significantly enhancing their migration and invasion." (PMID 40826474, 2025). "Studies show that the lncRNA HAGLROS packaged in tumor-derived exosomes promotes M2 macrophage polarization and EMT via the miR-135b-3p/COL10A1 axis, providing a plausible link between EV-ncRNA profiles and resistance phenotypes in the tumor microenvironment." (PMID 41463084, 2025). "In vitro and in vivo experiments confirmed that NU7441 effectively blocks COL10A1+Fib-induced tumor proliferation, migration, EMT, and immune suppression." (PMID 40826474, 2025). "Recent studies, using single-cell RNA sequencing (scRNA-seq) analyses, have revealed that COL10A1 is predominantly overexpressed in the tumor stroma of several solid cancers, including breast, pancreatic, and gastrointestinal tumors." (PMID 41303526, 2025). "While COL10A1+Fib and rCOL10A1 individually promoted tumor growth, NU7441 treatment reversed their pro-tumorigenic effects." (PMID 40826474, 2025). "Building on these findings, our study is the first to reveal the role of COL10A1+Fib as a central communication hub connecting tumor cells, immune cells, and the extracellular matrix." (PMID 40826474, 2025). "ChIP-qPCR confirmed that RUNX2 directly binds to Site1 and Site2 of the COL10A1 promoter, and multiplex immunofluorescence further showed co-localization of RUNX2 and COL10A1 in fibroblasts (Primary Tumor: n = 35), indicating direct transcriptional activation." (PMID 40826474, 2025). "Most current studies on COL10A1 have primarily focused on its expression and function in tumor cells, while investigations into its role within CAF subpopulations—particularly COL10A1+Fib—remain limited." (PMID 40826474, 2025). "Our results showed that COL10A1 functions as a driver for tumor progression by promoting proliferation, migration, and invasion along with EMT through activation of important oncogenic pathways." (PMID 41303526, 2025). "The COL10A1 expression was significantly elevated in PCa, and its upregulation has been connected with tumour aggressiveness and a weak predictive outcome in subjects." (PMID 39656597, 2024). "This coincides with increased COL10A1 expression found in breast cancer specimens (n = 125) compared to normal breast tissue (n = 18) from the Clinical Proteomic Tumor Analysis Consortium." (PMID 39716322, 2024). "Our previous experiments showed that SYNPO2L, through COL10A1, interacts with CAFs to drive tumor progression and metastasis." (PMID 39247832, 2024). "Collectively, the present study outcomes confirm that COL10A1 performs a significant function in promoting tumour development of PCa by enhancing progression, migration and invasion, besides suppressing apoptosis by the PI3K/AKT pathway activation." (PMID 39656597, 2024). "Considering that TCGA data are from patient tumor samples, which include immune or tumor microenvironments, and our data indicating that COL10A1 requires interaction with CAFs to exhibit differential effects, we co-cultured cells with CAFs." (PMID 39247832, 2024).
tumor (continued). "In vivo experiments involving subcutaneous injection of MC38 cells into nude mice showed that knocking down COL10A1 increased epithelial tumor cells, while overexpression led to a notable increase in mesenchymal tumor cells." (PMID 39247832, 2024). "Our research discovered that tumor cells can also secrete COL10A1, which works in conjunction with CAFs." (PMID 39247832, 2024). "COL10A1, which belongs to the collagen family, has been observed to have significant expression levels in the majority of tumour tissues." (PMID 39656597, 2024). "Studies have shown that COL10A1 is highly expressed in a variety of tumor tissues and plays an important role as a regulatory hub in the evolution of malignancy." (PMID 39198393, 2024). "Studies have shown that COL10A1 can promote tumor fibroblast enrichment, thereby facilitating tumor metastasis." (PMID 39247832, 2024). "Tumor infiltration levels differed with different CNV of COL10A1, infiltration levels of CD4+ T cell (P<0.01) were lower with chromosome arm-level deletion and gain of COL10A1." (PMID 37006317, 2023). "COL10A1 protein expression levels of seventy-seven tumor tissue and five corresponding adjacent normal tissue from BLCA patients were analyzed by immunohistochemical staining, and high COL10A1 protein expression is associated with poor survival." (PMID 37006317, 2023). "These analyses showed that COL10A1 was involved in regulating the immunity of the tumor microenvironment in BLCA, especially in CD4+T cells, CD8+T cells, and M2 macrophages." (PMID 37006317, 2023). "GIPIA2, TIMER, and CIBERSORT algorithms were utilized to explore the effect of COL10A1 on the tumor immune microenvironment." (PMID 37006317, 2023). "In the BRCA model, tumour proliferation was largely impeded in the group with COL10A1 knockdown matCAFs, as evidenced by notably smaller tumour weights compared with control group." (PMID 38148640, 2023). "To deeply confirm the role of COL10A1 in the tumor immune microenvironment, we took advantage of the CIBERSORT algorithm to evaluate the levels of 22 types of immune cells." (PMID 37006317, 2023). "Further analysis demonstrated that the COL10A1 protein was strikingly correlated to the pathological stage (P< 0.05) and tumor grade (P< 0.05)." (PMID 37006317, 2023). "Protein expression analysis showed that COL10A1 protein was significantly high-expressed in tumor tissues compared with adjacent normal tissues (P<0.001)." (PMID 37006317, 2023). "The RNA-seq data from the TCGA database were used to compare COL10A1 expression between tumor samples and adjacent normal tissues using the R language and TIMER database." (PMID 37006317, 2023). "High COL10A1 mRNA levels were correlated with more advanced tumor stage in BLCA (p < 0.001), COAD (p < 0.01), ESCA (p < 0.001), KIRC (p < 0.001), KIRP (p < 0.001), PAAD (p < 0.05), STAD (p < 0.001), TGCT (p < 0.05) and THCA (p < 0.001)." (PMID 38147021, 2023). "COL10A1 expression data was acquired from 33 paired tumor and normal samples from TCGA database, and the expression disparities were assessed using TCGA and GTEx databases." (PMID 38147021, 2023). "In this study, we investigated the differential expression of COL10A1 in normal and tumor tissues and its prognostic value in PAAD using TCGA, the GEPIA, and the GEO databases." (PMID 36105715, 2022). "Recent studies have found that the overexpression of COL10A1 enhances the epithelial-mesenchymal transition of tumors and promotes tumor aggressiveness and disease progression." (PMID 36105715, 2022). "In vivo studies confirmed that CAFs accelerated LUSC tumor growth, and this effect was counteracted by COL10A1 silencing." (PMID 36246404, 2022). "Of particular interest is the very strong correlation of elevated COL10A1 transcription with CAFs, as those pool of cell populations are emerging as modulators of establishing a pro-invasive tumor microenvironment." (PMID 36267978, 2022).
tumor (continued). "Consistent with what we observed for LOX and LTBP2, we found that COL10A1, which was the only tumor-specific protein, is strongly increased in tumor tissue (p = 5.93e-06), when compared with paired normal adjacent mucosa." (PMID 35340765, 2022). "Based on recent studies, abnormal COL10A1 expression in many cancer types has promoted the tumor growth." (PMID 36276283, 2022). "It would be interesting to study the correlation of MACC1 and COL10A1 activation in the analysis of bulk tumor specimen and in functional studies applying genetic COL10A loss of function models." (PMID 36267978, 2022). "Confirmatory studies in patient-matched tumor cell/CAFs co-culture systems are needed to analyze COL10A1 protein/DNA as component of the lateral information system between tumor cells and stroma environment." (PMID 36267978, 2022). "LUSC tumor cells with or without (COL10A1-silenced) CAFs were subcutaneously inoculated in nude mice to evaluate the effect of COL10A1 in CAFs on LUSC tumor growth." (PMID 36246404, 2022). "Correlation analysis showed that the expression level of COL10A1 was negatively correlated with the tumor purity of PAAD, indicating its relative enrichment in the tumor microenvironment." (PMID 36105715, 2022). "Both paired and unpaired results displayed the higher COL10A1 expression in tumor tissues relative to control adjacent tissues." (PMID 36276283, 2022). "The scatter plot shows the correlation between COL10A1 expression levels and the abundance of six tumor-infiltrating immune subgroups in PAAD." (PMID 36105715, 2022). "We present new evidence that tumor tissue collagen type X alpha 1 (COL10A1) is a relevant candidate biomarker to improve this dilemma." (PMID 36267978, 2022). "The expression of COL10A1 was increased in various solid human tumor tissues, which contributed to tumor vasculature staining." (PMID 32043519, 2020). "Among them, the expression of COL1A1, COL10A1 and COL11A1 was particularly higher, and that of COL4A4, COL6A5 and COL14A1 was especially lower in tumor tissues, indicating their possible roles as diagnostic markers for ESCC." (PMID 31598423, 2019). "Semi-quantitative scoring indicated that both SOX9 and COL10A1 protein levels were significantly higher in tumor tissues." (PMID 30154451, 2018). "Knockdown of COL10A1 showed a significantly decreased growth rate and tumor vessel density compared with scramble group." (PMID 30154451, 2018). "To further investigate the correlation between SOX9 and COL10A1 expression in vivo, we performed QPCR and western blot analysis using 30 pairs of tumor tissues (T) and adjacent normal gastric mucosa (N)." (PMID 30154451, 2018). "Expression of MMP11 and COL10A1 increased significantly from pDCIS to DCIS of DCIS/IBC mixed tumours." (PMID 30236106, 2018). "There was also a significant increase in the expression of MMP13 (P = 0.0169), S100P (P = 0.0234) and COL10A1 (P = 0.024) compared with expression in the corresponding non-tumor tissue." (PMID 27857161, 2016). "Notably, expression of COL10A1 mRNA exhibited a significant increase in tumor tissues, suggesting that expression of this gene is highly tumor-specific." (PMID 41373732, 2025). "Additionally, we identified NU7441 as a small-molecule inhibitor that attenuates COL10A1+Fib activity and its tumor-promoting effects." (PMID 40826474, 2025). "COL10A1+Fib promotes tumor cell proliferation, immune suppression, and metastasis." (PMID 40826474, 2025). "This suggests that cell-specific changes in COL10A1 expression can drive tumor progression and that increased expression in myoepithelial cells might have an anti-invasive effect." (PMID 39716322, 2024). "Therefore, we conducted several experiments and found that SYNPO2L regulates the secretion of COL10A1 by tumor cells, thus guiding the occurrence of tumor metastasis." (PMID 39247832, 2024). "Our research has also found that COL10A1 can chemotactically enrich tumor fibroblasts." (PMID 39247832, 2024).
tumor (continued). "Strikingly, examining the source of collagen gene expression (COL1A1, COL1A2, COL3A1, COL6A1, COL8A1, COL10A1) provided clarity that the majority of genes expressed in the tumor samples represent transcripts of the MSC-related component of the tissue microenvironment." (PMID 36940196, 2023). "Tumor immune infiltrating analyses showed that COL10A1 might have an essential role in recruiting infiltrating immune cells and regulating immunity in BLCA, thus affecting prognosis." (PMID 37006317, 2023). "Notably, the ablation of COL10A1 in matCAF within cancer tissue significantly reduced tumour progression." (PMID 38148640, 2023). "COL10A1 was found to be enriched in the tumor as a part of the collagen family." (PMID 38147021, 2023). "In combination with the analysis results, COL10A1/FAP/FN1 were mainly positively correlated with most of the tumor immune cells, which might be associated with an enhanced tumor immune response." (PMID 38063927, 2023). "M2-polarized macrophages are contributors to play a role in pro-tumor and anti-inflammation activity, which may be the underlying reason for the poor prognosis in BLCA patients with high COL10A1 expression." (PMID 37006317, 2023). "COL10A1 was positively associated with CD276, which is an immune checkpoint molecule that plays a vital role in regulating the malignant cellular-biological behaviour of tumours." (PMID 37974070, 2023). "Intratumoral administration of miR-101-3p modified human primary BM-MSC EVs in BALB/c nude mice with SCC resulted in a decrease in COL10A1 expression, with a consequent reduction of tumor volume and weight and the invasion, migration and colony-forming ability of the cells." (PMID 37239847, 2023). "To further investigate the correlation between COL10A1 expression levels and TIICs, we investigated the relationship between COL10A1 expression levels and infiltration levels in six tumor-infiltrating immune subpopulations using immune cell markers corresponding to different immune cells." (PMID 36105715, 2022). "Results showed an increase in COL10A1 protein in tumor tissue, and in BGN and FAP proteins involved in collagen fibril assembly and matrix degradation, respectively, emphasizing that these hub genes could have a crucial function in gastric tumorigenesis." (PMID 35328635, 2022). "Interestingly, our proteomic analysis has uncovered three proteins that were present either in tumor ECM alone (COL10A1) or in tumor and adjacent mucosa (EFEMP2 and vWF) and were absent in most distant mucosa samples." (PMID 35340765, 2022). "Also, COL10A1 exhibited overexpression in tumor tissue from TCGA database relative to normal tissue; hence, COL10A1 expression shall be validated via other studies, such as RT-PCR and Western blot." (PMID 36276283, 2022). "High COL10A1 expression exhibited an obvious relation to tumor T and pathologic stage." (PMID 36276283, 2022). "COL10A1 mRNA levels in tumor material is clinical and molecular prognostic, featuring upregulation compared to non-cancer tissue, increase with histomorphological malignancy grading of the tumor, elevation in tumors that invade perineural areas, or lymph node invasion." (PMID 36267978, 2022). "In this study, we found the relevance of COL10A1 expression to tumor-filtrating immune cells, namely, CD8 T cells, cytotoxic cells, DC, eosinophils, iDC, macrophages, mast cells, NK CD56dim cells, NK cells, pDC, T helper cells, Tem, Th1 cells, Th17 cells, and Treg." (PMID 36276283, 2022). "Notably, elevated expression collagen-associated genes, including COL10A1 and COL1A1, was observed in tumor tissues when compared to normal tissues." (PMID 34758833, 2021). "Other undiscussed signaling pathways may indicate that the COL10A1 gene is also involved in the regulation of non-tumor diseases." (PMID 33371777, 2021). "In addition, in GC patients, COL10A1 expression levels had been distinct in groups classified as per the pathological stage, tumor differentiation and T stage." (PMID 33371777, 2021).